REST (RE1 silencing transcription factor)
Diseases named in the same sentence as REST in open-access papers (continued):
Sharing a sentence is not in itself a finding about the gene and the disease.
glioblastoma (continued). "Recent work has highlighted the role of the transcription factor RE1 Silencing Transcription Factor, REST in glioblastoma but how REST function correlates with disease outcome has not been described." (PMID 23216891, 2012). "Moreover, silencing of REST by siRNAs resulted in the reduction in cell proliferation and migration capacities in U-87 and U-251 glioblastoma cells." (PMID 40006989, 2025). "Due to the strong negative correlation between REST and HAR1A, we have hypothesized that the oncogenic activity of REST in glioblastoma was at least in part mediated by HAR1A silencing." (PMID 39602392, 2024). "First, we noted that REST knockout led to the activation of genes related to fatty acid metabolism, and then we observed that the addition of pan-ACSL (acyl-CoA synthetase long-chain) inhibitor Triacsin C was able to suppress this compensatory event in REST-KO glioblastoma cells." (PMID 38609948, 2024). "Reducing REST levels in REST-dependent glioblastoma tumors holds promising therapeutic effects." (PMID 38609948, 2024). "Indeed, all the genes from the list were additionally validated by qPCR assay in two glioblastoma REST-KO clones." (PMID 38609948, 2024). "Taken together, these results suggest glioblastoma cells vary in their REST protein level." (PMID 38609948, 2024). "Our study also demonstrated direct therapeutic relevance of REST targeting in glioblastoma." (PMID 27698411, 2016). "Using this REST gene signature we predict that REST function is enhanced in advanced glioblastoma." (PMID 23216891, 2012). "To further investigate the function of REST in GBM, we performed wound scratch assay and measured gene expression of commonly used GSC (glioblastoma stem cells) markers, respectively." (PMID 38609948, 2024). "Our results contribute to recent findings regarding the promise of REST inhibition in high REST glioblastoma cells and combination regimens targeting GBM plasticity." (PMID 38609948, 2024). "One of the deregulated genes in GBM is a repressor element-1 silencing transcription factor (REST), a transcriptional repressor that has been identified as an oncogenic protein in various brain tumor types, including neuroblastoma, medulloblastoma, and glioblastoma." (PMID 38609948, 2024). "However, as the non-enhancing region contains both invasive glioblastoma cells and surrounding parenchyma and this change is consistent with comparison to healthy brain controls, we are unable to comment on expression of REST in invasive glioblastoma relative to core in these samples." (PMID 39602392, 2024). "With regards to central nervous system (CNS) tumors, several studies have found that REST expression level is high in neuroblastoma, medulloblastoma and glioblastoma (GBM)." (PMID 34859007, 2021). "Here we examined REST expression in human glioblastoma multiforme (GBM) specimens and its role in GBM cells carrying self-renewal and tumorigenic competence." (PMID 22701651, 2012). "The REST gene signature may have important clinical implications for the treatment of glioblastoma." (PMID 23216891, 2012). "RAS suppressor neurofibromin 1 is differentially spliced to a less active isoform in >80% of HGG downstream from REST upregulation, activating the RAS/MAPK pathway and reducing glioblastoma patient survival." (PMID 35102191, 2022). "To further investigate the clinical relevance of REST and HAR1A/HAR1B expression, we compared the expression of these genes in a publicly available dataset of glioblastoma samples taken from MRI contrast enhancing (CE) tumour core and non-enhancing (NE) tumour periphery regions." (PMID 39602392, 2024). "This hypothesis is supported by previous results showing that in glioblastoma, TRF2 can bind to and increase protein stability of another CSC-related transcription factor, the repressor element 1 silencing transcription factor (REST)." (PMID 34638302, 2021).
glioblastoma (continued). "To study the effect of REST on GBM proliferation, we used CRISPR-Cas9 to generate REST-knockout (REST-KO) homozygous cells from a representative glioblastoma cell line, T98G, containing high REST protein amount." (PMID 38609948, 2024). "Our results revealed that, regardless of whether the glioblastoma cells were sensitive or resistant to TMZ, erianin did not alter REST expression." (PMID 39039049, 2024).
Parkinson disease (19 papers, 2009 to 2025). A progressive degenerative disorder of the central nervous system characterized by loss of dopamine producing neurons in the substantia nigra and the presence of Lewy bodies in the substantia nigra and locus coeruleus. "In brains with Parkinson's disease and dementia with Lewy bodies, NRSF/REST is partially sequestrated in Lewy bodies and is mostly absent from the nucleus of neurons." (PMID 35850767, 2022). "In human Parkinson’s disease brains, REST protein has been found within cytoplasmic protein aggregates suggesting that protein inclusions, such as Lewy bodies, can sequester the protein and prevent nuclear translocation." (PMID 33185010, 2021). "In the first, the Parkinson’s disease was investigated in vitro by epigenetic modulations of the REST gene expressed in the neural SH-SY5Y cell line treated with MPP+." (PMID 31905747, 2019). "Another neurodegenerative disease, in which, however, the role of REST had been considered only marginal, is Parkinson’s disease that in Europe affects 1.2 million patients, corresponding to 7.5% of the REST-dependent population." (PMID 31905747, 2019). "In Parkinson’s and Alzheimer’s, therefore, the development of neurodegeneration appears to depend not on major increases, but rather on the nuclear concentration of active REST." (PMID 31905747, 2019). "We showed that REST was overexpressed in SIRT6-KO brains and cells; however, it was inactive, similar to what is observed in patients with AD and Parkinson’s." (PMID 39511137, 2024). "Whilst in Parkinson’s disease, nuclear translocation of REST does not occur in dopaminergic neurons of the substantia nigra (SN) or neocortex." (PMID 33185010, 2021). "In contrast, in human neuropathological diseases, including AD and Parkinson’s disease which are both hallmarked by protein misfolding and aggregation, REST does not translocate to neuronal nuclei to exert its protective functions." (PMID 33185010, 2021). "In the brains of individuals who have Parkinson’s disease (PD) and dementia with Lewy bodies (DLB), REST is generally absent from the nucleus of neurons and is primarily sequestered in Lewy bodies." (PMID 37326903, 2023).
prostate carcinoma (19 papers, 2016 to 2024). A carcinoma that arises from epithelial cells of the prostate gland. "REST expression negatively correlates with prostate cancer recurrence and mediates AR associated gene repression." (PMID 33572108, 2021). "Recent studies have reported that REST can inhibit the occurrence of tumors, and REST gene deletion or mutation is closely related to the occurrence of many tumors such as small-cell lung cancer, prostate cancer, and ovarian cancer." (PMID 33834072, 2021). "In prostate cancer, loss of REST is associated with the emergence of the most aggressive form of the disease, NEPC, featuring its known characteristics, notably the loss of AR signaling, and induction of genes related to neuroendocrine differentiation, such as CHGA, a target gene of REST." (PMID 33572108, 2021). "All these results together indicate that CREB1 signaling induces NE markers through repressing REST expression in prostate cancer cells." (PMID 38777812, 2024). "Our study provides evidence that CREB1 signaling represses REST mRNA and protein expression during neuroendocrine differentiation of prostate cancer cells." (PMID 38777812, 2024). "The effect of REST overexpression in the 22rv1 cell line (xenograft-derived prostate cancer) on EMT, migration, invasion, and the viability for ENZ was evaluated." (PMID 38542313, 2024). "As expected, REST expression negatively correlates with NE markers in prostate cancer patient samples." (PMID 38777812, 2024). "In the literature, there have been several elegant studies documenting the repression of REST function in prostate cancer through the mechanisms of alternative splicing and protein degradation." (PMID 38777812, 2024). "In the human prostate carcinoma cell line LNCaP, REST repressed IB1/JIP-1 to regulate the neuronal phenotype and JNK signaling pathway." (PMID 37892159, 2023). "Dysregulation of REST can be observed in the lung cancer as well as in aggressive prostate cancer (PCa)." (PMID 36650528, 2023). "The role of REST in NEPC has been further supported through its ability to suppress interleukin-6 induced neuroendocrine differentiation in prostate cancer cells." (PMID 33572108, 2021). "Proteomics of a unique set of 17 prostate cancer-derived PDXs indicated a role of REST in regulating neuronal gene expression in prostate cancer cells, thus favoring neuroendocrine differentiation of these cells." (PMID 31366128, 2019). "Moreover, we found that REST cDNA overexpression in PC3 cells reversed NE marker induction by the activation of CREB1 signaling by Fsk+IBMX, which suggests that REST downregulation is essential for CREB1’s induction of NE markers in prostate cancer cells." (PMID 38777812, 2024). "We next investigated how ADT downregulates REST transcription in prostate cancer cells." (PMID 38777812, 2024). "To investigate the role of REST in prostate cancer progression, we modulated REST expression via cDNA over-expression and shRNAs knock-down systems in prostate cancer cells, followed by examining NE marker expression and phenotypes of prostate cancer cells in vitro and in vivo." (PMID 38777812, 2024). "As expected, REST represses NE markers and prostate cancer progression." (PMID 38777812, 2024). "Notably, ADT-activated CREB1 signaling enhances EZH2’s epigenetic repression of REST, which in turn induces NE markers in prostate cancer cells." (PMID 38777812, 2024). "Furthermore, altered REST splicing was also found to mediate the anti-tumor effects of SRRM4 targeting in prostate cancer cells." (PMID 37892159, 2023). "Considering that EHMTs are part of the REST complex responsible for repressing neuronal genes, we further investigated whether EHMT1/2-regulated genes were associated with NE transformation in prostate cancer." (PMID 37663929, 2023).
prostate carcinoma (continued). "Another study implemented on neuroendocrine differentiation in prostate cancer cells revealed that knockdown of REST activates the IL-6-induced autophagy, while IL-6-induced neuronal cell morphology changes in prostate cancer cells were significantly inhibited due to the REST overexpression." (PMID 34819125, 2021). "Loss of REST/NRSF and increased REST4 splicing were identified in a subset of aggressive breast tumors and also positively correlated to development of castration-resistance prostate cancers with neuroendocrine phenotype." (PMID 32244895, 2020). "Although the effects of the AR on gene repression are largely unknown, a previous report suggested that the repressor element (RE)-1 silencing transcription factor (REST) mediates the effects of AR on suppression of brain-derived neurotrophic factor (BDNF) in prostate cancer cells." (PMID 27144435, 2016). "It remains an interesting question for future investigation regarding how the EZH2-REST relationship evolves during prostate cancer progression, from REST being an EZH2 partner in prostate adenocarcinoma cells to REST becoming an EZH2 target in NEPC cells." (PMID 38777812, 2024). "We found that REST levels are reduced, while p-S133-CREB1 (an indicator of CREB1 activation) and NE markers are increased, when prostate cancer cells are treated with ISO or Fsk+IBMX." (PMID 38777812, 2024). "To determine the expression patterns of REST in adenocarcinoma and neuroendocrine prostate cancer (NEPC), we analyzed its expression patterns in a panel of androgen-dependent prostate cancer and NEPC cell lines, and patient samples." (PMID 38777812, 2024). "To better understand the mechanisms of NED in prostate cancer cells, here we investigated the links between ADT, CREB1, EZH2, and REST." (PMID 38777812, 2024). "DNA methylation and demethylation, histone modification, REST (RE1 silencing transcription factor), and polycomb group proteins among others participate in prostate cancer development." (PMID 35317831, 2022). "Here, combined RNA-seq and ChIP-seq analysis reveals that REST is involved in epithelial-mesenchymal transition (EMT) and stemness acquisition in NE differentiated prostate cancer (PCa) cells via direct transcriptional repression of Twist1 and CD44." (PMID 28256535, 2017). "To test this hypothesis, we first treated prostate cancer cells with known compounds that either enhance or inhibit CREB1 signaling, followed by examining REST and NE marker expression." (PMID 38777812, 2024). "Given that we have illustrated that REST is a direct target of EZH2 in NEPC cells, next, we set out to determine the genetic relations of the three proteins on this CREB1-EZH2-REST pathway in the context of ADT-induction of NE markers in prostate cancer cells." (PMID 38777812, 2024). "Indeed, treating several prostate cancer cell lines with GSK126, an inhibitor of EZH2, resulted in REST induction and reduced NE marker ENO2 expression." (PMID 38777812, 2024). "Thus, the study of PDXs contributed to better understand the role of REST, a transcription factor inducing EMT in prostate cancer cells and stemness acquisition via direct transcriptional repression of Twist1 and CD44." (PMID 31366128, 2019). "For example, AR activity in prostate cancer cells may be modulated by RNAs, including the long non-coding RNA (lncRNA) HOTAIR, or by proteins, such as the transcriptional repressor RE1-silencing transcription factor (REST; also called neuron-restrictive silencer factor [NRSF])." (PMID 31116991, 2019).
small cell lung carcinoma (18 papers, 2010 to 2025). Small cell lung cancer (SCLC) is a highly aggressive malignant neoplasm, accounting for 10-15% of lung cancer cases, characterized byrapid growth, and early metastasis. "Single-cell and spatial protein transcriptomics have identified RE1 silencing factor (REST) as a potential biomarker for small cell lung cancer, associated with low neuroendocrine features, increased anti-tumor immunity, and prolonged survival." (PMID 39609317, 2024). "In prostate and small cell lung cancer gene dysregulation mediated by REST and the expression of REST variants are associated with a neuroendocrine phenotype." (PMID 37301955, 2023). "In small-cell lung cancer cells (SCLCs), A splice variant of REST with a 50-bp insert predicting a truncated REST was highly expressed." (PMID 37892159, 2023). "Additionally, REST gene deletion and frame-shift mutations are frequently observed in colon and small cell lung cancers." (PMID 35573698, 2022). "For example, in small cell lung cancer cells, the expression of REST is undetectable while a small cell lung cancer specific isoform of REST is highly expressed." (PMID 31041193, 2019). "The function of the tumor suppressor RE1 silencing transcription factor (REST) is lost in colon and small cell lung cancers and is known to induce anchorage-independent growth in human mammary epithelial cells." (PMID 20548947, 2010). "A series of recent studies have suggested that SRRM4 may play a role in the progression of small-cell lung cancer and NE prostate cancer by inactivating the RE1-silencing transcription factor (REST), in turn promoting expression of neuronal genes." (PMID 33621242, 2021). "For instance, REST may function as tumor suppressor in prostate cancer, small cell lung cancer, colon cancer, Wilms tumor, and breast cancer while function as oncogene in medulloblastoma and glioma." (PMID 31041193, 2019). "In small-cell lung cancer (SCLC) cell lines, a low-level expression of REST was observed which resulted in the expression of neuronal markers like the L1-cell adhesion molecule (L1-CAM) and neural cell adhesion molecule (NCAM)." (PMID 40006989, 2025). "Using intratumoral heterogeneity in small-cell lung cancer as a tractable model system, we uncovered a role for the transcriptional regulators REST and YAP as promoters of the neuroendocrine to non-neuroendocrine transition." (PMID 35577801, 2022). "Shue and colleagues further identify the REST and YAP transcriptional regulators as key components of the Notch signaling pathway in the control of the neuroendocrine cell fate in lung development, lung injury response, and small-cell lung cancer." (PMID 35577801, 2022).
mild cognitive impairment (15 papers, 2015 to 2025). "In healthy aging, cells induce REST expression to protect cells from age-related stress; however, in mild cognitive impairment and AD, REST manifests lower expression, likely contributing to more severe symptoms." (PMID 41293128, 2025). "In Mn-exposed mice, REST deletion in the striatum led to worsened dopaminergic dysfunction, motor deficits, cognitive impairments, inflammation, and reduced glutamate transporter GLT-1." (PMID 40278152, 2025). "The blockade of REST prevented abnormal γ‐band oscillations and cognitive impairment after febrile convulsions and protected the integrity and function of the dentate gyrus." (PMID 36065764, 2022). "Conditional deletion of REST in the mouse brain leads to age-related neurodegeneration and nuclear REST is decreased in mild cognitive impairment and Alzheimer’s brains, while elevated REST levels are associated with the preservation of cognitive functions in aged humans." (PMID 34855580, 2021). "We next asked whether REST induction in aged individuals with no cognitive impairment (NCI) but with early AD pathology is associated with repression of CDK5 and GSK3β." (PMID 37919281, 2023). "Depression-like, anxiety-like, and cognitive impairment caused by indoxyl sulfate were accompanied by indoxyl sulfate CNS accumulation, impaired neuronal cell survival and neurogenesis, disturbed BDNF, serotonin, corticosterone, and REST expression, oxidative stress, and neuroinflammation." (PMID 33621199, 2021). "Human neurons show increased REST expression during normal healthy aging, but REST is not found in neurons of individuals with mild cognitive impairment and AD." (PMID 36072299, 2022). "To explore the role of REST in the aging brain, we examined nuclear REST levels in prefrontal cortical (PFC) neurons in aging individuals with no cognitive impairment (NCI) or clinically diagnosed AD from the ROSMAP cohort." (PMID 37919281, 2023).